RNU6-1243P (RNA, U6 small nuclear 1243, pseudogene)
Gene: Small nuclear RNA gene on chromosome 11 (61,937,894 to 61,938,000, forward strand). Ensembl gene ENSG00000200898.
Homologues: Orthologues: chimpanzee U6 (99% identical). Paralogues in human: RNU6-43P (91% identical), RNU6-727P (91% identical), RNU6-1060P (90% identical), RNU6-24P (90% identical), RNU6-1094P (89% identical), RNU6-1152P (89% identical), RNU6-11P (89% identical), RNU6-199P (89% identical), RNU6-19P (89% identical), RNU6-37P (89% identical), RNU6-41P (89% identical), RNU6-543P (89% identical), and 1283 more.